SLC10A5 (solute carrier family 10 member 5)
Synonyms: P5
Tractability: Antibody: UniProt predicts a signal peptide or a membrane-spanning region; the Human Protein Atlas places it where antibodies can reach. PROTAC: its protein half-life has been measured.
Gene: Protein-coding gene on chromosome 8 (81,693,631 to 81,695,058, reverse strand). Ensembl gene ENSG00000253598.
Subcellular location: Membrane
Subcellular location (Human Protein Atlas): Nuclear bodies; Nucleoplasm; Plasma membrane
Gene Ontology:
Molecular function: bile acid:sodium symporter activity
Biological process: bile acid and bile salt transport
Cellular component: plasma membrane; membrane
Genetic constraint (gnomAD): Loss-of-function variants: 0 observed, 0.0766 expected, observed/expected ratio (o/e) 0, 90% interval 0 to 1.89. That is too few expected variants to judge how well the gene tolerates losing a copy. Missense variants: 474 observed, 521.86 expected, observed/expected ratio (o/e) 0.91, 90% interval 0.84 to 0.98. Synonymous variants: 180 observed, 192.69 expected, observed/expected ratio (o/e) 0.93, 90% interval 0.83 to 1.06.
Homologues: Orthologues: chimpanzee SLC10A5 (99% identical), macaque SLC10A5 (96% identical), rat Slc10a5 (71% identical), mouse Slc10a5 (70% identical), Caenorhabditis elegans Y71G10AR.4 (22% identical), Drosophila melanogaster CG11655 (19% identical), Drosophila melanogaster CG9903 (18% identical). Paralogues in human: SLC10A3 (36% identical), SLC10A2 (22% identical), SLC10A4 (20% identical), SLC10A1 (18% identical), SLC10A6 (17% identical).